BANF1 (barrier to autointegration nuclear assembly factor 1)
Description:
Non-specific DNA-binding protein that plays key roles in mitotic nuclear reassembly, chromatin organization, DNA damage response, gene expression and intrinsic immunity against foreign DNA. Contains two non-specific double-stranded DNA (dsDNA)-binding sites which promote DNA cross-bridging. Plays a key role in nuclear membrane reformation at the end of mitosis by driving formation of a single nucleus in a spindle-independent manner. Transiently cross-bridges anaphase chromosomes via its ability to bridge distant DNA sites, leading to the formation of a dense chromatin network at the chromosome ensemble surface that limits membranes to the surface. Also acts as a negative regulator of innate immune activation by restricting CGAS activity toward self-DNA upon acute loss of nuclear membrane integrity. Outcompetes CGAS for DNA-binding, thereby preventing CGAS activation and subsequent damaging autoinflammatory responses. Also involved in DNA damage response: interacts with PARP1 in response to oxidative stress, thereby inhibiting the ADP-ribosyltransferase activity of PARP1. Involved in the recognition of exogenous dsDNA in the cytosol: associates with exogenous dsDNA immediately after its appearance in the cytosol at endosome breakdown and is required to avoid autophagy. In case of poxvirus infection, has an antiviral activity by blocking viral DNA replication. (Microbial infection) Exploited by retroviruses for inhibiting self-destructing autointegration of retroviral DNA, thereby promoting integration of viral DNA into the host chromosome. EMD and BAF are cooperative cofactors of HIV-1 infection. Association of EMD with the viral DNA requires the presence of BAF and viral integrase. The association of viral DNA with chromatin requires the presence of BAF and EMD.
Synonyms: BAF; BCRP1; D14S1460; NGPS
Tractability: PROTAC: ubiquitination databases record sites on it; its protein half-life has been measured.
Gene: Protein-coding gene on chromosome 11 (66,002,228 to 66,004,170, forward strand). Ensembl gene ENSG00000175334.
Subcellular location: Nucleus; Chromosome; Nucleus envelope; Cytoplasm
Subcellular location (Human Protein Atlas): Nucleoplasm; Cytosol
Pathways (Reactome):
Disease: 2-LTR circle formation; APOBEC3G mediated resistance to HIV-1 infection; Autointegration results in viral DNA circles; Integration of provirus; Integration of viral DNA into host genomic DNA; Vpr-mediated nuclear import of PICs
Cell Cycle: Initiation of Nuclear Envelope (NE) Reformation; Nuclear Envelope Breakdown
Gene Ontology:
Molecular function: double-stranded DNA binding; identical protein binding; protein binding; protein homodimerization activity; DNA binding
Biological process: chromatin organization; mitotic nuclear membrane reassembly; negative regulation of cGAS/STING signaling pathway; negative regulation of innate immune response; negative regulation of protein ADP-ribosylation; negative regulation of type I interferon production; negative regulation of viral genome replication; response to oxidative stress; chromosome organization; response to virus
Cellular component: chromatin; chromosome; condensed chromosome; cytoplasm; cytosol; nuclear envelope; nucleoplasm; nucleus
Genetic constraint (gnomAD): Loss-of-function variants: 0 observed, 10.47 expected, observed/expected ratio (o/e) 0, 90% interval 0 to 0.29. The upper end of that interval is the gene's LOEUF score, 0.29, which puts it in group 1 of 6, group 1 being the genes least tolerant of losing a copy. Missense variants: 47 observed, 113.98 expected, observed/expected ratio (o/e) 0.41, 90% interval 0.32 to 0.53. Synonymous variants: 49 observed, 44.48 expected, observed/expected ratio (o/e) 1.1, 90% interval 0.88 to 1.4.
Gene-disease validity (ClinGen):
ClinGen rates the evidence that BANF1 causes each of these diseases.
Nestor-Guillermo progeria syndrome (autosomal recessive): Limited. A premature aging syndrome, autosomal recessive, characterized by lipoatrophy, osteoporosis, and very severe osteolysis.
Homologues: Orthologues: chimpanzee BANF1 (100% identical), dog BANF1 (100% identical), guinea pig BANF1 (100% identical), mouse Banf1 (97% identical), rat Banf1 (97% identical), zebrafish banf1 (82% identical), Caenorhabditis elegans baf-1 (60% identical). Paralogues in human: BANF2 (40% identical).
Diseases named in the same sentence as BANF1 in open-access papers:
BANF1 is named in the same sentence as 66 diseases in open-access papers, as found by Europe PMC text mining. Sharing a sentence is not in itself a finding about the gene and the disease. The quoted sentences say what the papers report.
Nestor-Guillermo progeria syndrome (17 papers, 2014 to 2025). "Together, our data indicates that the A12T mutation of BANF1, found in Nestor-Guillermo Progeria syndrome, causes a disruption of the DNA binding surface, inhibiting its normal interaction with double stranded DNA." (PMID 25495845, 2014). "Despite the available data on BANF1 biology, the contribution of the A12T mutation to the development of Nestor-Guillermo Progeria Syndrome is poorly understood." (PMID 25495845, 2014). "Given that it has been previously shown that exogenous expression of Nestor-Guillermo progeria syndrome-associated Banf1 A12T mutation induces aberrations in nuclear morphology, we next investigated if a similar phenotype was induced by the Banf1 variants selected for this study." (PMID 34820387, 2021). "Nestor-Guillermo progeria syndrome (NGPS) is caused by recessive mutations in the BANF1 gene." (PMID 30140252, 2018). "Nestor-Guillermo progeria syndrome (NGPS) is an autosomal recessive syndrome caused by a homozygous mutation of the BANF1 gene (c.34G > A; p.Ala12Thr), with only two cases." (PMID 39125589, 2024). "Mutation in the BANF1 (Barrier to Autointegration Factor 1) gene which encodes the BAF1 Lamin-associated protein are linked to the Nestor-Guillermo progeria syndrome (NGPS) clinically resembling HGPS." (PMID 27602048, 2016). "Nestor-Guillermo progeria syndrome (OMIM 614008) arises due to mutations in the BANF1 gene (11q13.1) coding for BAF protein, which is an interacting partner for, among others, emerin and lamin A/C complexes with chromatin." (PMID 30691039, 2019). "Highlighting the importance of nuclear envelope proteins, mutations in genes encoding several of these proteins are associated with human diseases including Emerin (Emery-Dreifuss Muscular Dystrophy), Lamin A/C (Hutchinson-Gilford progeria syndrome) and Banf1 (Nestor-Guillermo progeria syndrome)." (PMID 34820387, 2021).
progeria (14 papers, 2016 to 2025). "Apart from the role of BANF1 in nuclear envelope integrity, mutations in its gene can cause a human progeroid syndrome, and it appears that BANF1 is also crucial for restoring the capacity to repair oxidative lesions." (PMID 36316035, 2023). "In humans, mutations in Banf1 result in progeria, whereas single nucleotide polymorphisms in Cnksr2 are associated with human longevity." (PMID 34306034, 2021). "In comparison, some individuals with progeroid syndrome encode a homozygous mutation in Banf1 that impairs protein stability and is associated with fibroblasts having nuclear lamina abnormalities." (PMID 32156810, 2020). "Mutations in the genes LMNA and BANF1 can lead to accelerated aging syndromes called progeria." (PMID 35269487, 2022). "Nonetheless, a homozygous recessive mutation of BANF1 was identified in three individuals with NGPS, causing a rare type of progeria." (PMID 36980188, 2023). "Mutations in LMNA, EMD and BANF1 are genetically linked to many tissue-specific disorders including Emery-Dreifuss muscular dystrophy and cardiomyopathy (LMNA, EMD), lipodystrophy, insulin resistance and type 2 diabetes (LMNA) and progeria (LMNA, BANF1)." (PMID 31024910, 2019). "Lessel et al21 tested 50 patients with a putative diagnosis of nonclassical WS (ie, progeroid syndrome without WRN, LMNA, BANF1, and ZMPSTE24 mutations) and found causative POLD1 mutations in 8 patients." (PMID 30023403, 2018).
viral infection (12 papers, 2009 to 2025). "A deficiency in Banf1 is associated with reduced viral infection." (PMID 32156810, 2020). "BANF1 is a nuclear envelope protein involved in a variety of biological processes such as mitosis, viral infection, chromatin and gene regulation, and DNA damage responses." (PMID 36813848, 2023). "Inactivating Banf1 in cells leads to increased accumulation of host DNA in the cytoplasm, increased ISG expression mediated by cGAS/STING, and increased susceptibility to viral infection, suggesting Banf1 as a factor that regulates basal ISG expression." (PMID 34372578, 2021).
laminopathies (9 papers, 2016 to 2024). "Primary laminopathies include those diseases caused by variants in LMNA, whilst secondary laminopathies are caused by variants in other genes encoding proteins which are playing some role in prelamin A maturation (ZMPSTE24) or in lamin A/C function (BANF1)." (PMID 29557732, 2018). "Interestingly, different sets of mutations in the LMNA gene and genes coding for interacting proteins, such as emerin (EMD/STA gene) and BAF (barrier-to-autointegration, BANF1 gene), give rise to a variety of genetic disorders collectively called laminopathies." (PMID 30691039, 2019).
premature aging syndrome (7 papers, 2011 to 2024). Changes in the organism associated with senescence, occurring at an accelerated rate. "Strikingly, a point mutation in Banf1, alanine 12 to threonine (A12T), is associated with a severe premature ageing syndrome, Néstor–Guillermo progeria syndrome (NGPS), characterised by pathologies usually associated with ageing, such as generalised lipoatrophy and severe osteoporosis." (PMID 31796734, 2019). "A rare homozygous p.Ala12Thr variant in the BANF1 gene, encoding barrier-to-autointegration factor (BAF), causes Néstor–Guillermo progeria syndrome, a premature aging syndrome." (PMID 38274568, 2024). "Whereas complete loss of BAF causes lethality in multiple organisms, the A12T missense mutation of the BANF1 gene in humans causes a premature aging syndrome, called Néstor-Guillermo Progeria Syndrome (NGPS)." (PMID 36842139, 2023). "This is significant as the Banf1 A12T mutant protein is expressed to similar levels in patient cells as wild-type Banf1 in normal cells, suggesting that it is the presence of the mutant protein that causes the pathology of the NGPS premature ageing syndrome and not the lack of Banf1 protein." (PMID 31796734, 2019).
cervical cancer (5 papers, 2015 to 2025). A primary or metastatic malignant neoplasm involving the cervix. "Recent research has linked elevated BANF1 expression to breast cancer, correlating with lymph node positive and pathological staging, and to differentiation in esophageal tumor and influencing the proliferation, migration, and invasion of cervical cancer." (PMID 38261746, 2024). "In cervical cancer, BANF1 knockdown significantly inhibits tumor cell clonogenicity, invasion, and migration, underscoring its role in cervical cancer progression." (PMID 40384864, 2025). "We also evaluated 3′-UTR alleles of BANF1 because this region is functionally important in cervical cancer, where BANF1 mRNA is suppressed by miRNA-203 via binding to 3′-UTR nucleotides 138–159." (PMID 31024910, 2019). "BANF1 expression was significantly higher in cervical cancer cells and tissues than in normal tissues." (PMID 25658920, 2015). "Our study establishes a linear signaling pathway from IRF1 to BANF1 that may contribute to BANF1-induced tumorigenesis in cervical cancer." (PMID 25658920, 2015).
HIV-1 infection (5 papers, 2009 to 2022). The type species of lentivirus and the etiologic agent of acquired immunodeficiency syndrome (AIDS). "These include host cell co-factor proteins that facilitate HIV-1 infection, such as BANF1 (O75531), importin (O95373), NPM1 (P06748), SNW domain-containing protein 1 (Q13573), and PCBP1 (Q15365)." (PMID 36325020, 2022).
gastric cancer (4 papers, 2020 to 2025). A primary or metastatic malignant neoplasm involving the stomach. "Database and experimental results revealed that BANF1 is localized in the nucleus of gastric cancer cells, with significantly elevated mRNA and protein expression levels in gastric cancer tissues and cell lines." (PMID 40384864, 2025). "Additionally, BANF1 knockdown significantly reduced the proliferation and migration capabilities of gastric cancer cells." (PMID 40384864, 2025). "For instance, BANF1 has been reported to be involved in colony formation, migration and invasion in CC and in the development of hepatocellular and esophageal squamous cell carcinomas and gastric cancer." (PMID 32204550, 2020).
breast carcinoma (3 papers, 2024 to 2025). "Bioinformatic analysis of patient samples demonstrated that Banf1 is overexpressed in all breast cancer stages and subtypes." (PMID 40664994, 2025). "Banf1 expression levels were highest in breast cancers that are typically most aggressive, including basal-like and stage IV cancers." (PMID 40664994, 2025). "Given frequent Banf1 overexpression in breast cancer samples, we investigated Banf1’s role in tumour cell growth." (PMID 40664994, 2025). "Overall, our findings demonstrate Banf1 overexpression in both breast cancer patient data and TNBC cellular models, suggesting that Banf1 may contribute to TNBC growth and survival." (PMID 40664994, 2025). "Furthermore, studies have shown that BANF1 can serve as a predictive biomarker for breast cancer and hepatocellular carcinoma." (PMID 39439799, 2024). "Kaplan-Meier analysis of the probability of relapse free survival (RFS) in breast cancer patients was negatively correlated with Banf1 expression, whilst there was no observable correlation between overall survival (OS) and Banf1 expression." (PMID 40664994, 2025).
esophageal squamous cell carcinoma (3 papers, 2023 to 2025). Esophageal squamous cell carcinoma (ESCC) is a type of esophageal carcinoma (EC) that can affect any part of the esophagus, but is usually located in the upper or middle third. "ROC curve analysis identified VRK1 and BANF1 as potential therapeutic targets for esophageal squamous cell carcinoma." (PMID 40384864, 2025). "In esophageal squamous cell carcinoma, the knockdown of VRK1 leads to the down-regulation of the barrier-to-autointegration factor 1 (BANF1)." (PMID 36770809, 2023).
colorectal cancer (2 papers, 2023 to 2025). A primary or metastatic malignant neoplasm that affects the colon or rectum. "Knocking down VRK1 in HT-29 and HCT-116 colorectal cancer cell lines led to reduced BANF1 protein levels, which was associated with inhibited cell proliferation and migration." (PMID 40384864, 2025).
lung carcinoma (2 papers, 2021 to 2024). "Next on the list was BANF1 (barrier to auto-integration factor 1), which is a candidate marker of lung cancer patient prognosis." (PMID 38790260, 2024).
motor neuron disease (2 papers, 2023 to 2024). "Here, we report the identification of an individual with progressive motor neuron disease that carries a dominant mutation in BANF1." (PMID 36980188, 2023).
ovarian carcinoma (2 papers, 2023 to 2025). A malignant neoplasm originating from the surface ovarian epithelium. "We found that the expression of BANF1, CDK2AP2, DDT, LRIG1, MRPL4, and S100A13 was upregulated in ovarian cancer samples, and the expression of EPS8, NUCB2, PAF1, PMP22, RABGAP1L, and USO1 was upregulated in normal samples." (PMID 41000388, 2025).
pancreatic cancer (2 papers, 2024 to 2025). "Recent clinical studies have shown that BANF1 expression is elevated in patients with pancreatic cancer and short survival times." (PMID 38261746, 2024).
tauopathies (2 papers, 2023). "Intriguingly, gene silencing of ANKLE2 and BANF1 resulted in some of the most potent effects on tau aggregation, yet little is known about the role of these genes in tauopathies." (PMID 36316035, 2023).
atherosclerosis (1 paper, 2023). A disease characterized by the build-up of fatty material and calcium deposition in the arterial wall resulting in partial or complete occlusion of the arterial lumen. "Since reducing the death of foam cells and SMCs is a therapeutic goal to prevent atherosclerosis development and worsening and to stabilize the lesion cap, in vivo BANF1 upregulation could have a role in decelerating foam cells and SMC death and in reducing plaque instability." (PMID 37570694, 2023).
colitis (1 paper, 2023). Inflammation of the colon. "After restoring TMIGD1 and BANF1, both WT and Tmigd1INT-KO mice with colitis exhibited increased body weight and colon length, less bloody diarrhea, and lower disease activity." (PMID 37542259, 2023). "We intraperitoneally injected adenovirus (ADV) to boost TMIGD1 and BANF1 expression in mice 2 days before inducing colitis with DSS." (PMID 37542259, 2023). "BANF1 protein was reduced in the inflamed colonic mucosa of patients with CD, DSS-, and TNBS-induced colitis compared with the corresponding control groups." (PMID 37542259, 2023).
colon cancer (1 paper, 2025). "In immunocompetent mice, BANF1 deficiency in tumor cells significantly inhibited tumor growth and enhanced the response to immunotherapy in a colon cancer model." (PMID 40384864, 2025).
head and neck squamous cell carcinoma (1 paper, 2024). A squamous cell carcinoma that arises from any of the following anatomic sites: lip and oral cavity, nasal cavity, paranasal sinuses, pharynx, larynx, and salivary glands. "However, the role of BANF1 in prognosis remains unclear in head and neck squamous cell carcinoma (HNSCC)." (PMID 39439799, 2024).
Huntington disease (1 paper, 2024). Huntington disease (HD) is a rare neurodegenerative disorder of the central nervous system characterized by unwanted choreatic movements, behavioral and psychiatric disturbances and dementia. "Gene set enrichment analysis (GSEA) showed that BANF1 expression was associated with the cell cycle, Huntington's disease, olfactory transduction, spliceosomes, and systemic lupus erythematosus." (PMID 38261746, 2024).
lymph node metastasis (1 paper, 2025). "High BANF1 expression correlated with poor differentiation, increased invasion depth, lymph node metastasis, advanced tumor stage, and reduced overall and disease-free survival rates." (PMID 40384864, 2025).
otosclerosis (1 paper, 2023). Formation of spongy bone in the labyrinth capsule which can progress toward the stapes (stapedial fixation) or anteriorly toward the cochlea leading to conductive, sensorineural, or mixed hearing loss. "Otosclerosis colocalized genetically with the expression of BANF1, MARK3 and SUPT3H in the highest number of tissues (14, 8 and 6, respectively), while the highest causal posterior probability was observed for TELO2 (9.5%), ZNRD2 (6.3%), EHBP1L1 (6.0%)." (PMID 36653343, 2023).
Parkinson disease (1 paper, 2023). A progressive degenerative disorder of the central nervous system characterized by loss of dopamine producing neurons in the substantia nigra and the presence of Lewy bodies in the substantia nigra and locus coeruleus. "BANF1, PCGF5, WDR5, RYBP and BRD2 are related to the immune process of Parkinson’s disease and can predict the occurrence of Parkinson’s disease, which is expected to become a new target for the diagnosis and treatment of Parkinson’s disease." (PMID 36813848, 2023).
psoriasis (1 paper, 2023). An autoimmune condition characterized by red, well-delineated plaques with silvery scales that are usually on the extensor surfaces and scalp. "In psoriasis, translocation of BANF1 from the cytoplasm to the nucleus suppresses the phosphorylation of c-Jun and mitigates cutaneous inflammation." (PMID 37542259, 2023).
Stroke (1 paper, 2023). Sudden impairment of blood flow to a part of the brain due to occlusion or rupture of an artery to the brain. "Our research findings highlight the significance of genes associated with the UPR pathway, including ATF6, EXOSC5, EEF2, LSM4, NOLC1, BANF1, and DNAJC3, in the occurrence of stroke." (PMID 37891634, 2023).